VEGFB (vascular endothelial growth factor B)
Diseases named in the same sentence as VEGFB in open-access papers (continued):
Sharing a sentence is not in itself a finding about the gene and the disease.
melanoma (10 papers, 2015 to 2025). A malignant, usually aggressive tumor composed of atypical, neoplastic melanocytes. "In summary, our results suggested that DANCR facilitated VEGFB expression and the sequential angiogenesis to enhance melanoma progression through directly binding with miR-5194." (PMID 37215458, 2023). "Furtherance, both our collected melanoma tissues and microarray data from TCGA data base showed positive correlation between DANCR and VEGFB in human melanoma tissues." (PMID 37215458, 2023). "For further verification, we knocked VEGFB down in shNC-melanoma cells to decrease the secreted VEGFB in the CM and added human recombinant VEGFB167 into the CM of shDANCR-melanoma cells." (PMID 37215458, 2023). "To verify the function of VEGFB in modulating DANCR-involved angiogenesis in melanoma, we investigated VEGFB expression in the subcutaneous xenograft tumors." (PMID 37215458, 2023). "Coincidentally, inhibition of VEGFB diminished the tube formation induced by shNC-melanoma cells and VEGFB167 reversed the reduction of tube formation caused by shDANCR-melanoma cells." (PMID 37215458, 2023). "Next, we used miR-5194 inhibitor to treat DANCR knockdown melanoma cells and found that miR-5194 inhibitor successfully reversed the reduction of VEGFB secretion and expression induced by DANCR downregulation." (PMID 37215458, 2023). "Moreover, expression of VEGFB was also decreased in melanoma cells with DANCR knockdown detected by both qRT-PCR assay and Western Blot assay." (PMID 37215458, 2023). "Our study revealed that DANCR increased angiogenesis in melanoma microenvironment through miR-5194/VEGFB signaling, targeting which might improve therapeutic effect." (PMID 37215458, 2023). "We found impaired HUVECs recruitment with CM from VEGFB downregulated shNC-melanoma cells." (PMID 37215458, 2023). "To investigate whether miR-5194 involved in DANCR regulating VEGFB, we overexpressed miR-5194 in melanoma cell (SFigure 3A) and found attenuated ability of promoting HUVECs tube formation in miR-5194-overexpressed (miR-5194-mimics) melanoma cells." (PMID 37215458, 2023).
colorectal cancer (9 papers, 2010 to 2024). A primary or metastatic malignant neoplasm that affects the colon or rectum. "Genes, such as HMOX1 and VEGFB, are important for the invasion of various cancer cells, such as bladder cancer and colorectal cancer, but these genes may be associated with the invasion of BRCA cells." (PMID 31311202, 2019). "Patients with advanced colorectal cancer receiving combined FOLFOX and bevacizumab have decreased VEGFB-mediated angiogenesis, including reduced myeloid cell-endothelial cell communication through VEGF as identified by scRNA-seq." (PMID 39761010, 2024).
breast carcinoma (8 papers, 2021 to 2025). "In Roquin2-overexpressing MDA-MB-468 and MCF7 cells, we found that proangiogenic factors mRNA, including PDGFC, ENG, EDN1, and VEGFB, were downregulated in two breast cancer cells, while the mRNA expression of antiangiogenic genes, including TIMP1/3, SERPINF1, and ANGPTL4 were upregulated." (PMID 34345214, 2021). "In line with the overexpression results, knocking down Roquin2 increased the mRNA levels of angiogenic genes, including ENG, EDN1, VEGFB, and PDGFC in breast cancer cells." (PMID 34345214, 2021).
ischemic heart disease (7 papers, 2014 to 2025). "Collectively, our findings provide mechanistic insight into cell death activation pathways, including ferroptosis, in response to ischemic stress and further validate the therapeutic potential of VEGFB in promoting CM survival in ischemic heart disease." (PMID 41148858, 2025).
Stroke (7 papers, 2009 to 2024). Sudden impairment of blood flow to a part of the brain due to occlusion or rupture of an artery to the brain. "Vascular endothelial growth factor-B (VEGF-B) protects against experimental stroke, but the effect of stroke on VEGF-B expression is uncertain." (PMID 23601533, 2013). "Since our earlier work suggested a proangiogenic effect in the CSF, we compared the concentrations of VEGFA and VEGFB in the CSF of both candesartan and saline treated animals at 24 hours after stroke." (PMID 21912702, 2011). "In our study, we only focused on the effects of VEGFA,VEGFB and their corresponding receptors to stroke recovery." (PMID 21912702, 2011). "Vascular restoration by candesartan after stroke maybe related to differential regional upregulation of VEGFB and VEGFA, promoting a “prosurvival state” in the ischemic hemisphere and angiogenesis in the contralesional side, respectively." (PMID 21912702, 2011). "Our earlier report of increased VEGF in the ischemic hemisphere of candesartan treated animals, reflected the inability of the nonspecific ELISA assay to differentiate between VEGFA and VEGFB and is a more common way to report VEGF quantification in the stroke literature." (PMID 21912702, 2011).
Cerebral ischemia (5 papers, 2013 to 2023). Restriction of arterial blood supply to the brain associated with insufficient oxygenation to support the metabolic requirements of the tissue. "We also examined the mRNA expression of VEGFA and VEGFB in mice and bEnd.3 cells, observed that levels of both were upregulated following cerebral ischemia/reperfusion." (PMID 36909178, 2023).
metabolic syndrome (5 papers, 2017 to 2022). A cluster of metabolic risk factors for CARDIOVASCULAR DISEASES and TYPE 2 DIABETES MELLITUS. "The aim of our study was to evaluate the association between VEGFb serum levels and the new-onset of metabolic syndrome (MS) and its components in the Spanish adult population after 7.5 years of follow-up." (PMID 35987953, 2022).
non-alcoholic fatty liver disease (5 papers, 2020 to 2024). "On the other hand, the VEGFB gene was downregulated; this vascular endothelial growth factor controls tissue lipid accumulation, and its inhibition reduces hepatic steatosis and non-alcoholic fatty liver disease in mice." (PMID 38834875, 2024).
cervical cancer (4 papers, 2017 to 2024). A primary or metastatic malignant neoplasm involving the cervix. "The moderate or high expression rate for VEGFA was 35.7% (n = 15), with 19 patients (45.2%) exhibiting moderate or high immunohistochemical staining for VEGFB in the cytoplasm of cervical cancer cells." (PMID 28072723, 2017).
cognitive decline (4 papers, 2021 to 2026). "Increased expression of VEGFR1 and its ligand VEGFB were associated with a more rapid rate of cognitive decline, providing evidence of a potential link between increased VEGFR-1 expression in AD pathogenesis." (PMID 42292330, 2026). "Prefrontal cortex expression of multiple VEGF genes, including ligand genes VEGFB and PGF and receptor genes FLT1 and FLT4, were associated with a more rapid rate of cognitive decline late in life, with VEGFB and FLT4 also associated with cognitive scores closest to death." (PMID 31332262, 2021). "Within the prefrontal cortex, higher expression of these four genes (VEGFB, FLT1, PGF, and FLT4) was associated with more rapid cognitive decline and higher pathology burden." (PMID 39641382, 2025). "Additionally, higher expression of VEGFB in oligodendrocytes (logFC = −0.561, FDR = 0.019) was also associated with faster cognitive decline." (PMID 39641382, 2025). "Furthermore, vascular endothelial growth factor B (VEGFB), important for BBB repair, increased with age and was further elevated in AD patients, aligning with its association with BBB disruption and cognitive decline." (PMID 41449219, 2025). "When we expanded our analyses to brain tissues we observed that VEGFB, FLT1, PGF, and FLT4 all appear to contribute to the progression of AD pathology and cognitive decline." (PMID 39641382, 2025).
diabetic cardiomyopathy (4 papers, 2018 to 2025). Diabetic cardiomyopathy is a disorder of the heart muscle in people with diabetes. "In this review, we will discuss the biology of VEGFB, and its relationship to diabetic cardiomyopathy." (PMID 29732375, 2018). "Hence, the therapeutic value of VEGFB in treating diabetic cardiomyopathy needs to be considered in relation to the possible accompaniment of retinopathy in these patients." (PMID 29732375, 2018).
endometrial carcinoma (4 papers, 2003 to 2021). A malignant tumor arising from the epithelium that lines the cavity of the uterine body. "Our results demonstrate that EIN harbors most of the driver events reported in EEC and for the first time we reported a high frequency of the amplification of VEGFB gene in endometrial cancer." (PMID 30886832, 2019). "The overwhelming majority of CNAs were amplification of genes, and the amplification of VEGFB gene was the most frequent CNA which was presented in 20/115 samples of which 19/20 were endometrial cancer (95%) and 1/20 were EIN (5%)." (PMID 30886832, 2019). "Vascular endothelial growth factor-B may thus act to suppress changes that favour the development of endometrial cancer." (PMID 12942123, 2003). "VEGFB, MMP9, and neutrophils may cooperatively regulate angiogenesis in the primary metastasis of endometrial carcinoma." (PMID 33363026, 2020). "So far, there is no research on the effect of VEGFB on the prognosis of endometrial cancer, and future studies are required to elucidate it." (PMID 30886832, 2019).
gastric cancer (4 papers, 2020 to 2022). A primary or metastatic malignant neoplasm involving the stomach. "TGFB2 and VEGFB were selected as risk predictors for both overall and disease-free survival highlighting the role of TGFB and PI3K/AKT pathway in gastric cancer." (PMID 34332586, 2021). "Simultaneously, TGFB2, VEGFB, COL10A1, ERG1 and EFNA5 composed risk model is a promising tool for assessment of gastric cancer survival." (PMID 34332586, 2021). "There is increased expression of VEGFB in gastric cancer, and clinical drugs such as apatinib and Zaltrap can effectively block its function 46-50." (PMID 32754268, 2020). "Finally, we established risk model based on key pathways ligands TGFB2, VEGFB, COL10A1, AREG and EFNA5 to predict gastric cancer survival." (PMID 34332586, 2021). "In gastric cancer, we found CTHRC1 was highly co-expressed with many factors, such as ACVRL1, ANGPTL3, ANGPTL4, NOTCH4, VEGFB, VEGFC etc., which have been proved to play an important role in angiogenesis in various cancer." (PMID 35928443, 2022).
Hypertension (4 papers, 2020 to 2024). The presence of chronic increased pressure in the systemic arterial system. "For PC1, shared genetic variants with diastolic blood pressure (ATXN2, GOSR2, NOS3, BAG3) and hypertension (ATXN2, VEGFB, NOS3, BAG3) were also observed." (PMID 39543113, 2024).
infarction (3 papers, 2016 to 2021). A localised pathological necrosis of tissue resulting from obstruction of the blood supply usually by a thrombus, an embolus, or vascular torsion. "Vascular endothelial growth factor-B (VEGF-B) and angiopoietin 1 (ANGPT-1) are the main angiogenic factors that enhance endothelial cell proliferation and accelerate vascular growth in the infarction zone." (PMID 34204341, 2021). "Vascular endothelial growth factor-B (VEGF-B) and angiopoietin 1 (ANGPT-1), are the main angiogenic factors which enhance the proliferation of endothelial cells and speed the vascular regrowth within the infarction area." (PMID 30186566, 2018).
lymph node metastasis (3 papers, 2019 to 2024). "Previous studies demonstrated that VEGFA/C/D promotes tumor LYM and lymph node metastasis; however VEGFB has not been reported." (PMID 38638428, 2024).
metastatic colorectal cancer (3 papers, 2020 to 2024). "Recently, aflibercept (a vascular endothelial growth factor B (VEGFB) inhibitor) was also approved for the adjuvant treatment of metastatic colorectal cancer." (PMID 32380712, 2020).
angiosarcoma (2 papers, 2013 to 2019). A malignant tumor arising from the endothelial cells of the blood vessels. "Indeed, compared to other sarcomas, angiosarcoma tumors exhibited higher expression levels of endothelial marker/functional genes including PECAM1, EPHA2, ANGPT2, ENDRB, PGF, FLI1, VWF and reduced expression levels in KIT, VEGFA, and VEGFB." (PMID 25374893, 2013).
Arthritis (2 papers, 2011 to 2018). Inflammation of a joint. "Further studies have shown a role for VEGFB as a pro-angiogenic mediator in arthritis induced synovial angiogenesis." (PMID 21266048, 2011).
atherosclerosis (2 papers, 2014 to 2021). A disease characterized by the build-up of fatty material and calcium deposition in the arterial wall resulting in partial or complete occlusion of the arterial lumen. "In analyses of non-AD pathology, VEGFB was positively associated with atherosclerosis (β = 0.006, SE = 0.003, and p = 0.039) and arteriolosclerosis (β = 0.008, SE = 0.003, and p = 0.013)." (PMID 31332262, 2021). "Many of the genes differentially regulated during monocyte-to-macrophage differentiation (downregulated genes include JAK2, STAT6, TLR8, and TLR2, and upregulated genes include VEGFB, TGFB1, FN1, IL-1R2, SCARB1, MSR1, and CD163) have been previously reported in the pathogenesis of atherosclerosis." (PMID 25011540, 2014).
breast tumor (2 papers, 2021 to 2023). "Our recent study confirms this idea, where a cyclic peptidomimetic based on the helix α1 of VEGFB and a motif situated in its proximity bound to both VEGFR1 and VEGFR2 and inhibited angiogenesis and breast tumor growth." (PMID 37375853, 2023).
fibrosis (2 papers, 2021 to 2023). the formation of excess fibrous connective tissue in an organ or tissue in a reparative or reactive process. "The first model utilised only serum TGs as an explanatory variable, and the second added adipose VEGFB expression to the model, utilising both TGs and adipose VEGFB expression as the explanatory variables for the NAFLD status (steatosis, fibrosis, and NASH)." (PMID 37224770, 2023).
glioma (2 papers, 2021 to 2025). A benign or malignant brain and spinal cord tumor that arises from glial cells (astrocytes, oligodendrocytes, ependymal cells). "P2X7R was also upregulated in the glioma microenvironment and its expression was linked to the expression of VEGFB, MMP9, PCNA, IL-4 and IL-8." (PMID 41034696, 2025). "Taken together, these data demonstrate that significant P2X7R expression in high-grade glioma samples was positively associated with VEGFB expression, and inversely associated with IL-4, IL-8, MMP-9 and PCNA, demonstrating a potentially pro-tumour angiogenic capacity." (PMID 41034696, 2025). "P2X7R-mediated VEGFB secretion might also contribute to glioma angiogenesis by boosting VEGFA activity." (PMID 41034696, 2025).
head and neck squamous cell carcinoma (2 papers, 2023 to 2024). A squamous cell carcinoma that arises from any of the following anatomic sites: lip and oral cavity, nasal cavity, paranasal sinuses, pharynx, larynx, and salivary glands. "Moreover, VEGFA, VEGFB, VEGFC, and PGF expression was significantly increased in CHOL, head and neck squamous cell carcinoma (HNSC), KIRC, and LIHC tumor tissues." (PMID 37852616, 2023).
hepatocellular carcinoma (2 papers, 2018 to 2024). A malignant tumor that arises from hepatocytes. "In examining patients with hepatocellular carcinomas, researchers found that higher VEGFB expression correlated with advanced stage, multiple tumors, positive vascular invasion and lack of capsule formation." (PMID 29732375, 2018). "VEGFB expression can be found in many different tumor types and its expression has been found to be increased in multiple cancers such as renal carcinomas and hepatocellular carcinomas." (PMID 29732375, 2018).
lung adenocarcinoma (2 papers, 2024 to 2026). A carcinoma that arises from the lung and is characterized by the presence of malignant glandular epithelial cells. "Bioinformatics analysis confirmed elevated VEGFA and VEGFB mRNA expression in lung adenocarcinoma patients compared to healthy individuals." (PMID 42015273, 2026).
non-small cell lung carcinoma (2 papers, 2021 to 2025). A group of at least three distinct histological types of lung cancer, including non-small cell squamous cell carcinoma, adenocarcinoma, and large cell carcinoma. "A gene signature containing VEGFD plus VEGFA and VEGFB is a prognostic indicator in early-stage non-small cell lung cancer (NSCLC) through detecting multiple gene transcription levels by quantitative polymerase chain reaction." (PMID 34612148, 2021).
proliferative diabetic retinopathy (2 papers, 2017 to 2025). Advanced retinopathy due to diabetes mellitus characterized by the formation of new vessels in the retina. "MITF, a master regulator of the RPE differentiation and homeostasis, was footprinted on VEGFB proximal promoter (−2, TSS) and VEGFA, with major clinical relevance in neovascular AMD and proliferative diabetic retinopathy." (PMID 40565279, 2025).
rosacea (2 papers, 2021 to 2025). A chronic erythematous skin disorder that affects the face. "VEGFA, rather than VEGFB was highly expressed in rosacea lesions." (PMID 34993194, 2021). "An anti-malarial drug, Artemisinin, decreased the expression of Angiopoietin 2 and VEGFC, but not VEGFA or VEGFB, in a mouse model of rosacea induced by LL37, the proinflammatory form of cathelicidin, and showed a beneficial clinical effect in rosacea patients." (PMID 41562711, 2025).
steatosis (2 papers, 2022 to 2023). Increased lipid within the cytoplasm of cells. "We observed that HFD caused hepatocyte steatosis, and VEGFB gene knockout exacerbated the degree of hepatocyte steatosis." (PMID 35907871, 2022). "The scoring results revealed that compared with the SD and the HFD groups, VEGFB knockout mice hepatocyte bullae and microtubular showed observable steatosis changes, and hypertrophic hepatocytes and inflammatory cell aggregation also increased dramatically." (PMID 35907871, 2022).
Abdominal obesity (1 paper, 2022). Excessive fat around the stomach and abdomen. "Moreover, results about the association between VEGFb categories and the development of the individual components of MS have shown that only abdominal obesity incidence by ATP-III criteria is associated with VEGFb levels." (PMID 35987953, 2022). "Adjusted logistic regression analysis showed that the likelihood of developing MS and abdominal obesity was statistically reduced in subjects included in the higher VEGFb category." (PMID 35987953, 2022). "Low serum levels of VEGFb may be considered as early indicators of incident MS and abdominal obesity in the Spanish adult population free of MS, independently of other important predictor variables." (PMID 35987953, 2022). "All these together might explain why in our study subjects with lower VEGFb levels would be more prone to developing abdominal obesity and MS, in comparison to those with higher VEGFb levels." (PMID 35987953, 2022). "Our results indicate that VEGFb may be considered an early indicator of abdominal obesity development in the Spanish adult population without MS." (PMID 35987953, 2022).
Cognitive impairment (1 paper, 2021). Abnormal cognition is characterized by deficits in thinking, reasoning, or remembering. "At the same time, a higher expression of VEGFB, FLT4, FLT1, and PGF in the prefrontal cortex was related to the stronger cognitive impairments in patients indicating impaired neural network function." (PMID 33672819, 2021).
hip osteoarthritis (1 paper, 2025). "Further ligand-receptor interaction analyses showed that the VEGFA, VEGFB and CXCL8 associated interaction pairs were significant in the crosstalk between neutrophil and endothelium in hip osteoarthritis (HOA) group which may enhance the angiogenesis." (PMID 40169566, 2025).